HK2 (hexokinase 2)
Diseases named in the same sentence as HK2 in open-access papers (continued):
Sharing a sentence is not in itself a finding about the gene and the disease.
lung cancer (continued). "Activation of glycolysis pathway by exogenous expression of HK2 could induce invasiveness and metastasis of control lung cancer cells." (PMID 33809182, 2021). "Also, HK2 was required for tumour initiation and maintenance in a mouse model; its inhibition suppressed the malignant behaviour of breast and lung cancer, both in vitro and in vivo." (PMID 34664737, 2021). "Finally, we show that collagen XVII, Oct4 and HK2 are valuable markers to predict the prognosis of patients with lung cancer." (PMID 31928533, 2020). "The transcription factor BACH1 could activate HK-2 transcription and increase glucose uptake, glycolytic rate, and lactate secretion, thereby stimulating glycolysis-dependent metastasis of human lung cancer cells." (PMID 32489324, 2020). "In addition, we used CRISPR Cas9 HK1 deletion to create isogenic HK1−HK2+ and HK1+HK2+ H460 lung cancer cell lines." (PMID 29988332, 2018). "However, HK1+HK2+ cancer cell lines from a variety of cancers (liver, breast, colon, prostate, ovary, lung), including the lung cancer H460 cell line, are resistant to HK2 silencing alone or the synthetic lethality of the shHK2/DPI/PER." (PMID 29988332, 2018). "To determine whether HK1−HK2+ cancers of other origins will be sensitive to HK2 inhibition, we created isogenic HK1−HK2+ cells from HK1+HK2+ H460 lung cancer cells." (PMID 29988332, 2018). "Furthermore, we found that ORY-1001 inhibited lung cancer cell proliferation, cell cycle and induced apoptosis by triggering the Warburg effect, by regulating HK2 expression." (PMID 30568590, 2018). "In summary, these results indicate that ORY-1001 could inhibit the growth of lung cancer cells via regulating the Warburg effect by controlling HK2." (PMID 30568590, 2018). "However, in contrast with normal tissues, inhibition of HK2 by 2-DG suppresses lung cancer cell growth through induction of cell apoptosis and autophagy." (PMID 29285270, 2017). "We confirmed through this study that HK2 is overexpressed in NSCLC cell lines and lung cancer tissues, which implied that HK2 may has a crucial role during lung tumorgenesis." (PMID 28427230, 2017). "In above text, we mainly showed HK2 is essential for Kras-driven lung cancer at the genetic level." (PMID 26884725, 2016). "Recently, using an HK2 conditional knockout mouse, a group showed that HK2 is required for tumor initiation and maintenance in mouse models of KRas-driven lung cancer, lending further evidence that HK2 is a key metabolic driver in cancer, and an attractive target in cancer biology." (PMID 27588472, 2016). "We transfected Flag-HK2 plasmids in HCC827 and found increased HK2 can downregulate the cleaved-caspase 3 and reverse the viability, glucose consumption, and lactate production, which proved Daurisoline inhibited the proliferation of lung cancer dependent on HK2." (PMID 39699276, 2025). "Previous studies also have found that downregulating Hexokinases II (HK2)-mediated glycolysis by Deguelin or downregulating ATK-mediated glycolysis by miR-128 suppresses the progression of lung cancer, suggesting that glycolysis suppression might be a strategy for drug-resistant LUAD treatment." (PMID 35354796, 2022). "Furthermore, the inhibitory effects of phenformin on the proliferation of H292 ER cells were significantly decreased by HK2 overexpression, indicating that enhanced glycolysis reduces the anticancer effects of phenformin in lung cancer cells with acquired EGFR-TKI resistance." (PMID 34367462, 2021).
lung cancer (continued). "Finally, we showed that collagen XVII, Oct4, and HK2 could be valuable markers to predict the prognosis of lung cancer patients." (PMID 31928533, 2020). "Moreover, HK2 targeted by other miRNAs could modulate the glycolysis in various cancers, such as miR-199a-5p in liver cancer and miR-143 in breast and lung cancers." (PMID 29043013, 2017). "Furthermore, a recent study demonstrated HK2 to be essential for lung tumor initiation and maintenance; its systemic ablation conferred therapeutic efficacy in mouse models of lung cancer with Hk2 deletion, suppressing glucose-derived ribonucleotide synthesis in lung cancer cells." (PMID 27602772, 2016). "BACH1 suppresses mitochondrial activity by reprogramming the glucose utilization into glycolytic metabolism via upregulating the transcription of glycolytic genes, including HK2 and GAPDH, in lung cancer cells." (PMID 40263598, 2025). "BACH1 is able to activate the transcription of Hexokinase 2 and GAPDH and thereby promotes lung cancer metastasis." (PMID 38818308, 2024). "BACH1 activates the transcription of glycolytic enzymes hexokinase 2 (HK2) and GAPDH, thus increasing glucose uptake, glycolysis rates, and lactate secretion to promote KRAS-driven lung cancer metastasis." (PMID 39061897, 2024). "Our analysis of Kaplan–Meier plots derived from data on 1925 lung cancer patients clearly confirmed the strong oncogenic role of HK2, LDHA, PHGDH, PSAT1, SHMT2, MTHFD2, c-Myc, and ATF4 (CREB-2) in lung cancer." (PMID 37233697, 2023). "Human hexokinase 2 (HK2) is a glycolysis regulator that links metabolic and proliferative functions in various cancers such as breast and lung cancers, HCC and PCa." (PMID 35887358, 2022). "This positive feedback promotes c-Myc-mediated transcriptional regulation of HK2 and LDHA, accelerating the aerobic glycolysis of lung cancer." (PMID 35927226, 2022). "HK2 and GBE1 are regulated by hypoxia-inducible factor (HIF), enabling lung cancer cells to invade tissues using focal adhesion kinase activity." (PMID 35747059, 2022). "Bioinformatic analysis revealed the synergistic effect between the Set7/9 and either HIF1A, HK2, GLUT1, or LDHA expression levels on the survival outcome of lung cancer patients." (PMID 34692483, 2021). "All data together indicated that the downregulation of c-Myc, HK2, PKM2, LDHA, PHGDH, PSAT1, cyclin D1, and CDK6 in lung cancer cells was related to the ubiquitin-protein degradation pathway, which was the result that the USP28 was inhibited by SGH." (PMID 33572615, 2021). "It was recently demonstrated that HDAC5 together with HDAC4 enhanced glycolysis by inducing the upregulation of hexokinase 2 (HK2), which was critical for EMT induced by hypoexpression of 5′ AMP-activated protein kinase (AMPK) in lung cancer." (PMID 34178647, 2021). "Meanwhile, the overexpression of miR-155 targets HK2 and promotes glycolysis in NSCLC.In addition, miR-125b was upregulated in lung cancer cells correlating with a higher expression of p-Akt." (PMID 33916349, 2021). "In a model of KRAS-driven lung cancer, antioxidants stabilize the transcription factor BACH1, enhancing HK2 transcription and triggering a metastatic spread favored by glycolytic metabolism of cancer cells." (PMID 33946854, 2021). "A low expression of miR-124 in lung cancer cells shows a significant increment in glucose consumption and ATP production by upregulating GLUT1 and HK2 expressions, both of which are key enzymes in the rate-limiting step of the glycolytic pathway." (PMID 33916349, 2021). "Bioinformatic analysis has shown a synergistic impact of Set7/9 together with either GLUT1, HIF1A, HK2, or LDHA on the survival of lung cancer patients." (PMID 34692483, 2021). "For example, in mice bearing RB1 null lung cancer, upregulation of glucose transporter (GLUT) 1 and two rate-limiting enzymes in glycolysis, hexokinase-2 (HK2) and pyruvate kinase isozymes 2, was observed, suggesting that RB1 regulates glucose metabolism." (PMID 33627136, 2021).
lung cancer (continued). "Recently, study has found the inhibition of HK2 activated AMPK and thus suppressed its down-stream mTORC1 in lung cancer." (PMID 32831652, 2020). "The analysis of the TCGA database with TIMER showed that HK3 is significantly downregulated in lung cancer tissues, while HK1 and HK2 are significantly upregulated at the same time." (PMID 32508023, 2020). "Together, these results suggest that PD-L1 upregulates HK2 expression via the PI3K/Akt and Erk pathways, thereby increasing glycolytic activity in human lung cancer cells." (PMID 31718692, 2019). "In fact, it has been demonstrated that HK2 activation and glycolytic activity are required for protecting tumor cells, such as DLBCL, lung cancer, and prostate cancer, to enter into an adaptive process under hypoxic stress." (PMID 30944034, 2019). "We identified key factors affecting glucose uptake in lung cancer cell, including GLUT1, HK2, and p‐AKT." (PMID 31355526, 2019). "Activated BACH1 increases the transactivation of glycolysis genes such as Hexokinase 2 and Gapdh which stimulates the KRAS-driven lung cancer metastasis." (PMID 31884422, 2019). "Together, these data suggest that ORY-1001 affects the Warburg effect in lung cancer cells by targeting KDM1A, leading to the regulation of HK2 expression." (PMID 30568590, 2018). "In an effort to determine the role of HK2 in lung cancer mediated by KDM1A, we analyzed the correlation between HK2 expression levels and the outcomes of lung cancer patients." (PMID 30568590, 2018). "We also observed the expression of HK2, LCN2 and autophagy-related genes in lung cancer cell lines, including CL1-0, CL1-5, TL-6 and H1975 with or without 0.25 mM NiCl2." (PMID 29285270, 2017). "We mapped metabolic network, and showed that expressions of GBE1 and HK2 significantly upregulated and highly correlated with expression of HIF1 in lung cancer." (PMID 28423489, 2017). "In lung cancer, TRIM46 activates AKT/HK2 signaling by modifying PHLPP2 ubiquitination to promote glycolysis and chemoresistance, which reflects the importance of TRIM46/PHLPP2/AKT signaling in lung cancer and provides a new strategy for lung cancer treatment." (PMID 36249749, 2022). "Therefore, the effects of SGH on the glucose consumption, lactate production, and expression levels of the glycolytic regulators HK2, PKM2, and LDHA in lung cancer cells were investigated." (PMID 33572615, 2021). "We sought to investigate whether there are correlations between the expression levels of glycolytic genes HIF1A, GLUT1, HK2, and LDHA, in lung cancer patients and the rates of the patients’ survival." (PMID 34692483, 2021). "For example, in lung cancer, BACH1 activates the transcription of Hexokinase 2 and GAPDH, enhances the uptake of glucose of cancer cells, improves the glycolysis, and alleviates oxidative stress-induced damage of cancer cells, hence facilitating cancer cell metastasis." (PMID 34191748, 2021). "Overexpression of lncRNA-IGFBP4–1 via targeting HK2/PDK1/LDHA could affect energy metabolism and promote lung cancer progression." (PMID 33123468, 2020). "In this study, we demonstrated that upregulation of total PD-L1 expression raised glycolysis/HK2 expression of lung cancer cells in the absence of PD-1 ligation." (PMID 31718692, 2019). "Importantly, c-Myc knockdown in ZNF322A-silenced lung cancer cells reversed the suppression of LDHA and HK2 expression while reducing the upregulation of PGC1A." (PMID 30258097, 2019). "Both HK2 and LCN2 serve as biomarkers in lung cancer progression." (PMID 29285270, 2017). "Lastly, we found changes of some common pathways such as HIF1 signaling and metabolic pathways are involved in hypoxic-induced lung cancer cells; GBE1 and HK2 as independent unconventional clinical factors predicted survival in lung adenocarcinoma patients based on public microarray datasets." (PMID 28423489, 2017).
lung cancer (continued). "Interestingly, miR-143 can also inhibit HK2 expression in human lung cancer and neck squamous cell carcinoma (HNSCC) through targeting HK2." (PMID 29156804, 2017). "Additionally, a study indicated that BACH1 bound to the glycolytic gene Hexokinase 2 (HK2) and Glyceraldehyde-3-Phosphate Dehydrogenase (GAPDH) promoters, activated their expression and stimulated glycolysis rate, thereby promoting metastasis in lung cancer." (PMID 34351577, 2022). "Moreover, hexokinase 2 (HK2) and glyceraldehyde-3-phosphate dehydrogenase (GAPDH) have been identified among the strongest transcriptional targets of BACH1, suggesting that BACH1 stimulates glycolysis in lung cancer." (PMID 33499022, 2021). "Furthermore, BACH1 activates the transcription of HK2 (Hexokinase 2) and GAPDH (glyceraldehyde-3-phosphate dehydrogenase), enhancing glucose uptake, glycolytic flux, and lactate secretion, thereby promoting lung cancer metastasis through a glycolysis-dependent pathway." (PMID 40847302, 2025).
ovarian carcinoma (98 papers, 2015 to 2025). A malignant neoplasm originating from the surface ovarian epithelium. "It is of note that HK2 overexpression has been associated with chemoresistance in ovarian cancer and is an independent risk factor." (PMID 33160373, 2020). "Here, we showed that FOXK1 inhibits cellular senescence and promotes glycolysis and chemoresistance in ovarian cancer through regulating cell senescence- and glycolysis-associated proteins, such as P16, hTERT, HK2 and LDHA." (PMID 32550913, 2020). "In cells that overexpress HK2, enhanced autophagic response is observed, whereas, inhibition of HK2 causes suppression of autophagy, thus sensitizing resistant ovarian cancer xenografts to cisplatin." (PMID 32408513, 2020). "In ovarian cancer, elevated HK2 expression was significant associated with chemoresistance, suggesting that HK2 might contribute to cancer progression." (PMID 35953860, 2022). "However, the underlying molecular mechanism of HK2 in regulating cell proliferation and tumor formation in ovarian cancer cells still remains unilluminated." (PMID 35711830, 2022). "Likewise, a 2.5-fold upregulation of Glut1 and 0.5-fold increase in hexokinase 2 caused by downregulation of Hsulf-1 in ovarian cancer cells lead to glycolytic phenotype." (PMID 26887408, 2016). "Hexokinase-2 (HK2), which catalyzes the first step of glycolysis, is highly expressed in ovarian cancer cells." (PMID 40191206, 2025). "Ovarian cancer cells transport glucose into cells via GLUTs, Na+-independent sodium transporters, where hexokinase-2 phosphorylates glucose to glucose-6-phosphate." (PMID 39967908, 2025). "Another study on ovarian cancer showed that BBR inhibited the Warburg effect via the TET3/miR-145/HK2 pathways in ovarian cancer cells." (PMID 39896297, 2025). "Berberine, an alkaloid with antitumor properties, inhibits the Warburg effect in ovarian cancer cells by enhancing TET3-mediated demethylation via the TET3/miR-145/HK2 signaling pathway." (PMID 40191206, 2025). "In conclusion, we suggest that the mechanism behind GP‐2250's anti‐neoplastic effect on ovarian cancer cells includes inhibition of glycolysis via modulation of HK2 activation and expression and inhibition of HIF‐1α induced VEGF secretion." (PMID 39114948, 2024). "LncRNA KCNQ1OT1 can stabilize HK2 in osteosarcoma, colorectal cancer, and ovarian cancer, enhancing aerobic glycolysis and promoting cancer progression." (PMID 39609317, 2024). "Overexpression of miR-603 reduces glucose uptake and lactate production, and it also inhibits the proliferation, migration, and invasion of ovarian cancer cells by targeting HK2." (PMID 39609317, 2024). "A study on ovarian cancer found that degradation of HK2 occurred following the recognition of HK2-exposed KFERQ motifs by HSPA8 under conditions of cellular glucose deficiency." (PMID 37509689, 2023). "VDAC1 (Voltage Dependent Anion Channel 1) was shown to play a critical role in promoting cisplatin resistance in ovarian cancer by regulating the HSP70/HK2/VDAC1 signaling pathway." (PMID 38038814, 2023). "There was significantly higher expression of GLUT1 and HK2 in high-grade serous ovarian carcinoma (HGSOC) when compared to non-HGSOC and it was also associated with advanced stages of ovarian cancer." (PMID 37110218, 2023). "Consistently, in this study, exogenously expressed of HK2 also promoted cell growth in human ovarian cancer cells by accelerating cell cycle progression (up-regulated the expression of cell cycle-related factors, like cyclin A1, cyclin D1 and cyclin E1)." (PMID 35953860, 2022). "In this study, the clonogenic formation assay was used to detected the potential function of HK2 on regulating cell proliferation in human ovarian cancer cells." (PMID 35953860, 2022).